HOTAIR (HOX transcript antisense RNA)
Diseases named in the same sentence as HOTAIR in open-access papers (continued):
Sharing a sentence is not in itself a finding about the gene and the disease.
cancer (continued). "Considering HOTAIR can regulate gene expression and protein proteolysis, it has been reported that the lncRNA HOTAIR is dysregulated in the majority of human cancers." (PMID 34367966, 2021). "For its proven prognostic value, HOTAIR has also been suggested as a potential therapeutic target in human cancer." (PMID 34576322, 2021). "In cancer cells, the increased expression of HOTAIR allows this lncRNA to serve as a scaffold for the interaction of YBX1-pAKT and/or YBX1-pERK/pRSK, thereby leading to an increase in YBX1 S102 phosphorylation and subsequent nuclear translocation." (PMID 34266873, 2021). "HOTAIR is a biomarker for multiple cancers and is highly expressed in cancer tissues compared to normal tissues." (PMID 34482818, 2021). "Other interchromosomal targets of HOTAIR include cancer-related genes such as pro-calmodulin (PCDH), hepatic ligand protein receptor (EPHA1) and NF-κB inhibitory protein IκBα." (PMID 34887871, 2021). "More recently, a study indicated that HOTAIR and androgen receptor synergistically promoted tumor angiogenesis and cancer stemness in RCC cells both in vitro and in vivo." (PMID 34367966, 2021). "Considering berberine can reduce HOTAIR expression in vitro and in vivo, it has the potential to be an appropriate treatment for cancers such as NSCLC, where this lncRNA is increased." (PMID 33805687, 2021). "Three thyroid-specific genes (TG, TPO, and NIS), six cancer-associated lncRNAs (MALAT1, NEAT1, HOTAIR, H19, PVT1, MEG3), and two housekeeping genes (GAPDH and P0) were analyzed using Droplet Digital PCR (ddPCR)." (PMID 33030666, 2021). "HOTAIR is one of the major lncRNAs that is overexpressed ina variety of cancers and promotes cancer cell proliferation, invasion and migration." (PMID 39703905, 2021). "Limited effects on DNA replication and cell growth were found in HUF cells after HOTAIR knockdown, possibly due to a relatively lower HOTAIR level in HUF cells than in cancer cells." (PMID 33667269, 2021). "In fact, the overexpression of HOTAIR has been related to the evolution of some solid cancers with a crucial role in cancer initiation, progression, and drug sensibility modulation." (PMID 33540611, 2021). "In regulating tumorigenesis, lncRNA HOTAIR was reported to exert pro-cancer effects by inducing CSCs and EMT formation under the direct regulation of STAT3 under cigarette smoke exposure." (PMID 35047506, 2021). "Numerous studies have highlighted the aberrant cellular activity produced by the interaction of HOTAIR with different miRNAs during cancer development and progression." (PMID 33540611, 2021). "To further confirm the interaction between HOTAIR and miR-214-3p, we detected the change of miR-214-3p expression when HOTAIR expression was interfered in cancer cells." (PMID 34320988, 2021). "Other oncogenic lncRNAs such as H19, HULC, SNHG12, and HOTAIR also demonstrated their regulatory functions in promoting cancer cell proliferation, inhibiting apoptosis, and aggravating tumor progression." (PMID 34456631, 2021). "In particular, we analyzed, by Droplet Digital PCR (ddPCR), six cancer-associated lncRNAs (MALAT1, NEAT1, HOTAIR, H19, PVT1, MEG3) in both FNAs and surgical tissues." (PMID 33030666, 2021). "Elevated HOTAIR expression can be detected in both cancer cells and tumor tissues through qRT-PCR, in situ hybridization, and RNA-sequencing." (PMID 34367966, 2021). "Using this system and complementary experimental techniques, we additionally found that HOTAIR regulates cancer cell proliferation at least partially via interacting with YBX1, altering its subcellular localization and target gene transcription." (PMID 34266873, 2021). "HOTAIR is an oncogenic lncRNA and increased expression of HOTAIR is indicative of a poor prognosis in cancer patients." (PMID 34178644, 2021). "HOTAIR has been reported to be a key regulator of cancer, including colorectal, prostate, gastric, and ovarian cancer." (PMID 34064346, 2021).
cancer (continued). "In various cancers, HOTAIR is a well-known promoter of angiogenesis, as well as a promoter of cancer cell proliferation and invasion." (PMID 33809601, 2021). "A series of studies carried out with in vitro and in vivo models of rare cancers highlighted the fundamental role that HOTAIR has in these tumors and the complex network of molecular interactions in which it is involved." (PMID 34576322, 2021). "The expression of HOTAIR is frequently upregulated in different kinds of human cancer, including esophageal carcinoma, breast cancer, and lung and gastrointestinal tract carcinomas." (PMID 34395618, 2021). "Another lncRNA is HOTAIR, which has been shown to be overexpressed in different cancers and to promote malignant tumor characteristics." (PMID 34575316, 2021). "This interaction suppresses HOTAIR expression in an Ago2 (Argonaute2)-dependent manner, and reduces the proliferation and invasion ability of cancer cells." (PMID 33540611, 2021). "Specifically, six highly pathogenic irlncRNAs RP5-884M6.1, RP11-742B18.1, HOTAIR, AC004988.1, CTD-2357A8.3, and GS1-600G8.5, were found to be associated with cancer prognosis." (PMID 35082835, 2021). "Many studies reported functional interactions between HOTAIR and microRNAs able to modulate crucial cellular processes during cancer development." (PMID 33540611, 2021). "HOTAIR regulated the stemness of cancer stem cells through various approaches, among which HOTAIR interaction with definite miRNAs was generally accepted as an important mechanism." (PMID 34539782, 2021). "Current studiessuggest that HOTAIR lncRNA reprograms chromatinstate which can promote cancer metastasis." (PMID 31721532, 2020). "Some SE‐associated ce‐lncRNAs with high degree/betweenness were highly associated with cancer hallmarks, including lncRNAs reported in cancer (e.g., NEAT1, HOTAIR, XIST, and SNHG5)." (PMID 32460441, 2020). "Increased evidences have shown that HOTAIR controls key proteins and cellular pathways related to cell proliferation, migration, invasion, cancer stem cell-like differentiation, angiogenesis, and metastasis, while it inhibits apoptosis." (PMID 32466537, 2020). "We showed that overexpressed HOTAIR reversed BBR‐increased E‐cadherin protein expression; snail, which is a zinc finger transcriptional repressor and has been linked to cancer biology, was reported a direct target of the miR‐34 family." (PMID 32248643, 2020). "HOTAIR has been identified as an oncogene, promoting cancer metastasis through this guide capability." (PMID 32754048, 2020). "Factors that can regulate the expression of HOTAIR can provide new clues to cancer treatment and coping." (PMID 32117729, 2020). "Previous studies have reported HOTAIR overexpressed in various cancer types 17, which leads us to explore its function or its role in CRC." (PMID 32489462, 2020). "More and more studies have shown that the abnormal expression of HOTAIR is closely related to the different biological behaviors of human tumors and has gradually become a research hotspot in the field of cancer." (PMID 32700738, 2020). "HOTAIR has been shown to function as an oncogene since it is overexpressed in numerous cancers and is involved in physiological and pathological progression, including cellular proliferation, apoptosis, angiogenesis, invasion, and metastasis." (PMID 32462038, 2020). "Together, all these data imply that the contribution of HOTAIR to Doc resistance was attributable to its ability to increase the population of cancer stem cells." (PMID 32657763, 2020). "HOTAIR has been shown to enhance cancer cell energy metabolism in this kind of cancer through increasing HK2 expression." (PMID 33123468, 2020).
cancer (continued). "HOTAIR, which is over-expressed in different types of cancers, is a lncRNA that plays a role in carcinogenesis and cancer progression by promoting cancer cell viability, growth, and metastasis." (PMID 32752302, 2020). "Several other lncRNAs, such as MALAT1 and HOTAIR, also participated in diverse pathways in different cancer types." (PMID 32393270, 2020). "HOTAIR is highly expressed in various cancers, and induces the proliferation and metastasis of these cancers." (PMID 32394637, 2020). "Accumulating evidence proves that HOTAIR has crucial functions in the progression and metastasis of different cancers, such as breast, colorectal, non-small lung cell, and gastric cancer." (PMID 33133086, 2020). "For example, HOTAIR is known as an oncogenic lncRNA in various cancer types which affects cancer progress via forming HOTAIR/miRNA/mRNA axes." (PMID 32846981, 2020). "HOTAIR is overexpressed in different types of human malignancies and is involved in cancer progression and metastasis." (PMID 32083005, 2020). "Activity of estrogen receptor beta (ERβ), as a key factor in progression and invasion of many cancer types, has been reported to up-regulate HOTAIR in renal cell carcinoma." (PMID 32245498, 2020). "Specifically, knockdown of HOTAIR attenuates H3K27me3 of the E-cadherin promoter and derepresses H3K27ac, thereby increasing E-cadherin expression and consequently inhibiting cancer cell EMT." (PMID 32928281, 2020). "Ectopic expression of HOTAIR has been involved in drug resistance, increased cell proliferation and migration through multiple signalling mechanisms in cancer." (PMID 32248643, 2020). "HOTAIR levels are also a predictive cancer biomarker, and HOTAIR expression is highly correlated with patient prognosis." (PMID 32117729, 2020). "Oncogenic lncRNAs in human cancer, including HOTAIR, MALAT1, PCA3, CASC15, and CASC20 are also annotated in dogs." (PMID 33194754, 2020). "Indicated studies suggested HOTAIR as a competing long non-coding RNA decoying microRNAs targeting c-Met in different cancer contexts, and those microRNAs are reported to have different molecular targets in HCC rather than c-Met." (PMID 32650779, 2020). "On the basis of previous studies, we found that HOTAIR was up-regulated in many types of cancers, including NSCLC." (PMID 33193600, 2020). "The anti-cancer function of miR-601 also helps us better understand the tumor-promoting effect of HOTAIR in BC." (PMID 32694942, 2020). "In the present review, we summarize the role of HOTAIR in cancer progression and drug resistance, in particular in BC, and we illustrate the main approaches for silencing it." (PMID 32397382, 2020). "A recent and increasingly number of studies have suggested that HOTAIR can interact with miRNAs to regulate gene expression and cancer progression." (PMID 33375038, 2020). "The use of small molecules to modulate miRNA and lncRNA is currently being studied in cancer with promising results in the regulation of lncRNAs such as HOTAIR and MALAT1." (PMID 32754048, 2020). "A total of 231 lncRNAs have been identified as products of the HOX clusters, amongst which HOXD-AS1, HOXA-AS2, HOTAIRM1, HOTTIP, and HOTAIR, were reported to be involved in cancer regulation." (PMID 33375038, 2020). "The involvement of the long non-coding RNA, HOTAIR, in cancer development, progression, and metastasis is well-established." (PMID 32117729, 2020). "HOTAIR is known as a lncRNA with notable involvement in the reprogramming of chromatin organization and metastasis of cancer." (PMID 32279420, 2020). "These cancer phenotypes predominantly occur through HOTAIR-mediated epigenetic changes, which illustrates that lncRNA-guided mechanisms can be hijacked in the context of cancer." (PMID 32117729, 2020). "There is also one cancer-associated lncRNA that has been reported to be destabilized by TTP, namely HOTAIR." (PMID 32340118, 2020).
cancer (continued). "HOTAIR is deregulated in various cancers and can serve as a scaffolding to facilitate the recruitment of the PRC2 and LSD1/CoREST/REST complexes." (PMID 33291485, 2020). "Abnormal expression of HOTAIR exists in various human cancers including melanoma, hepatocellular carcinoma, gastric cancer, colorectal cancer and pancreatic cancer." (PMID 32209098, 2020). "The involvement of HOTAIR, a long non-coding RNA (lncRNA) in cancer development, progression, and metastasis is well-known." (PMID 32117729, 2020). "Nevertheless, definitive conclusion of predictive/prognostic effect of HOTAIR expression in this type of cancer still remains challenging." (PMID 31796041, 2019). "The decreased expression of HOTAIR leads to apoptosis, which has been induced by genistein in multiple types of cancer." (PMID 31208095, 2019). "HOTAIR acts as a vital cancer-promoting lncRNA in the BC process, and it was found to be up-regulated in the three described subtypes (ER-positive, HER2-positive and TNBC) of the disease." (PMID 31744046, 2019). "lncRNAs play an important role in cancer mainly via their associations with RNA-binding g proteins, which include HOTTIP, MaLAT1, H19, and HOTAIR." (PMID 31827401, 2019). "Further illustrating the mechanism of HOTAIR activation in tumor tissues holds promise for treating various cancers, including HCC." (PMID 31480503, 2019). "The overexpression of HOTAIR in various cancers, including UCC, indicates its important role in their development." (PMID 30813594, 2019). "On the other hand, it has been shown that downregulation of HOTAIR expression leads to activation of the PI3K-AKT-mTOR1 signaling pathway in most cancers." (PMID 31208095, 2019). "It was found that the miR-141 expression was upregulated, while the HOTAIR expression was downregulated, by genistein in cancer cells." (PMID 31208095, 2019). "Evidence supporting HOTAIR’s role in mediating drug resistance has emerged for many types of cancer investigated." (PMID 30654440, 2019). "Herein, we performed a meta-analysis to further investigate the prognostic value of HOTAIR expression in diverse human cancers." (PMID 31195674, 2019). "In effect, PTCSC3 should also interact with multiple factors to regulate LSCC cell proliferation because HOTAIR overexpression only partially rescued the inhibitory effect of PTCSC3 overexpression on cancer cell proliferation." (PMID 31171714, 2019). "The HOX Antisense Intergenic RNA (HOTAIR), which is overexpressed in a wide variety of cancers, including cervical cancer, is able to silence p21cip1/waf1 and promote cancer radio-resistance in vitro and in vivo." (PMID 31514410, 2019). "LncRNAs such as HOTAIR, MALAT1, GAS5, PC3, and H19 are aberrantly regulated in various malignant tumors and associated with carcinogenesis, metastasis, and prognosis." (PMID 31141943, 2019). "Taken together, due to its high affinity for HOTAIR, ADQ treatment efficiently blocked the HOTAIR/EZH2 interaction via the 36G46A binding site, thereby reversing HOTAIR-induced cancer progression and metastasis." (PMID 30764859, 2019). "Elevated HOTAIR expression was found to be significantly associated with OS, RFS/DFS and PFS/MFS in diverse types of cancers." (PMID 31195674, 2019). "HOTAIR is abnormally expressed in cancers and involved in regulating cancer proliferation, cell cycle and apoptosis." (PMID 30873207, 2019). "Altered expression of HOTAIR is found in many types of cancer, and promotes metastasis and tumor invasiveness through epigenetic gene silencing." (PMID 30654440, 2019). "Knockdown of HOTAIR enhances the sensitivity of cancer cells to chemotherapeutic agents like cisplatin and doxorubicin." (PMID 31141943, 2019). "So, the analysis of HOTAIR dysregulation and its correlation with this SNP can be proposed in different types of cancers in different population." (PMID 30873206, 2019). "HOTAIR is upregulated in many cancers, including GC, where HOTAIR increases the EMT and thereby facilitates metastasis." (PMID 31212809, 2019).
cancer (continued). "So, different studies have indicated the dysregulation of HOTAIR in different types of cancers in recent years." (PMID 30873206, 2019). "Aberrant HOTAIR expression has been detected in several human cancers showing a fundamental role in tumor proliferation, angiogenesis, progression, drug resistance and worse prognosis." (PMID 31072041, 2019). "So far, the roles of HOTAIR in cancer stemness, post-translational modifications, and drug resistance need to be further studied." (PMID 31480503, 2019). "In fact, higher levels of HOTAIR have been shown to promote cancer metastasis by modulation of PRC2-specific binding to chromatin, thus reprogramming the cell state to resemble the fibroblast condition." (PMID 30154449, 2019). "Knockdown of HOTAIR in orthotropic mice is able to attenuate the metastatic potential of tumor cells, blocking the crosstalk between CAFs and cancer cells." (PMID 31072041, 2019). "Of note, several studies suggest that HOTAIR expression is highly predictive of cancer patient survival rates in diverse cancer types." (PMID 31195674, 2019). "HOTAIR participate in cancer development and progression mainly by regulating chromatin dynamics and cancer cell behaviors." (PMID 31113870, 2019). "Herein, we conducted a comprehensive and updated meta-analysis to further investigate the prognostic value of HOTAIR expression for cancer patients." (PMID 31195674, 2019). "Increased HOTAIR expression was found to be strongly related to cancer recurrence (pooled HR = 1.84; 95% CI = 1.28–2.64; p = 0.001)." (PMID 31195674, 2019). "HOTAIR as a master regulator of chromatin dynamics is a well-characterized oncogenic lncRNAs in different types of human cancer." (PMID 31171714, 2019). "HOTAIR expression in epithelial carcinoma cells led to genome-wide re-targeting of PRC2 to an occupancy pattern more like embryonic fibroblasts, resulting in gene expression, increased cancer metastasis as well as invasiveness depend on PRC2." (PMID 31214490, 2019). "Recently, a growing number of studies have revealed HOTAIR contexts in the regulation of autophagy, cancer progression, and drug resistance." (PMID 30693021, 2018). "In recent studies, most of meta-analyses were conducted to focus on the association between lncRNA HOTAIR or lncRNA ZNRD1-AS1 or lncRNA POLR2E or lncRNA H19 polymorphisms and cancer risk." (PMID 29802154, 2018). "In laryngeal squamous cell carcinoma cells, HOTAIR is overexpressed and promotes CpG methylation in the promoter region of the tumor suppressor gene PTEN, resulting in the loss of PTEN in cancer cells." (PMID 29721215, 2018). "Abnormal expression of HOTAIR has been noticed for most of the cancers including, BT, BRC, CRC, GC, LVC, NSCLC, OVC, and PNC." (PMID 30693021, 2018). "By investigating the impact of HOTAIR inhibition and MKL1 knockdown in HeLa cells, we have shown that the effects of the migration and invasion in cancer cells of HOTAIR knockdown can be mimicked by the respective manipulation of MKL1 expression." (PMID 29391067, 2018). "HOTAIR has been shown to promote cancer cell proliferation, invasion and metastasis and it is therefore no surprise that HOTAIR has been shown to be overexpressed in several types of cancers." (PMID 29732012, 2018). "Recent studies of HOTAIR suggest that under heypoxia, HOTAIR expression is up-regulated in several cancer cells induced by the hypoxia-inducible factors (HIFs), recruiting hypoxia-response elements (HRE) to bind on the HOTAIR promoter." (PMID 30728830, 2018). "The findings above indicated that HOTAIR plays imperative roles in the modulation of cancer progression." (PMID 30111807, 2018). "We suggested that HOTAIR promotes cell migration and invasion of cancer cells through at least three mechanisms." (PMID 29391067, 2018). "For example, the lncRNAs TUG1, UCA1, SPRY4-IT1, HULC, HOTTIP, H19 and HOTAIR were found to be novel promising biomarkers for poor prognosis in human cancers." (PMID 29308050, 2018).